PSTPIP1 (proline-serine-threonine phosphatase interacting protein 1)
Diseases named in the same sentence as PSTPIP1 in open-access papers (continued):
Sharing a sentence is not in itself a finding about the gene and the disease.
Immunodeficiency (4 papers, 2022 to 2026). Failure of the immune system to protect the body adequately from infection, due to the absence or insufficiency of some component process or substance. "The mutations that alter the binding to LYP and other PEST phosphatases: R228C, D246N, E250Q, E250K and E257K, although few in number, represent around 50% of the patients with immune diseases associated to PSTPIP1 mutations." (PMID 35152348, 2022). "Furthermore, we identify a group of PSTPIP1 pathogenic mutations related to immune diseases that disrupt this interaction, indicating that the PSTPIP1/phosphatase complex is required for the normal physiology of the immune cells." (PMID 35152348, 2022). "The PSTPIP1 hub gene was related to T-cell activation, differentiation, and migration, modulating the function of innate immune cells and the innate immune response, and its mutation was confirmed as a crucial driver of immunodeficiency and auto-inflammatory diseases." (PMID 35571056, 2022). "Strikingly, exome sequencing also revealed variants in immunodeficiency-associated genes (IRAK4, USB1), autoinflammatory disorders (PSTPIP1) and unexpected candidates like ETV6, and MAN1B1 revealing previously unrecognised pathways in SLE development." (PMID 41930824, 2026). "PSTPIP1 (proline-serine-threonine phosphatase-interactive protein 1)–associated myeloid-related proteinemia inflammatory (PAMI) syndrome is a rare disease combined autoinflammatory and immunodeficiency." (PMID 36203570, 2022).
neutropenia (3 papers, 2021 to 2026). A decrease in the number of neutrophils found in the blood. "As one of the PSTPIP1-associated inflammatory diseases (PAIDs), neutropenia is a distinct manifestation to separate PAMI syndrome from other PAIDs." (PMID 36203570, 2022). "Neutropenia, hepatosplenomegaly, high myeloid-related protein 8 (MRP8) and MRP12 concentration are distinct manifestation to separate PAMI syndrome from PAPA syndrome, which is also caused by PSTPIP1 mutation." (PMID 36203570, 2022). "The specific clinical characteristics such as neutropenia with hepatosplenomegaly, hidradenitis suppurativa, and ulcerative colitis can help clinicians to diagnose whether the patient has PSTPIP1-related autoinflammatory diseases, and further genetic testing is needed to clarify the type of disease." (PMID 34620178, 2021).
glioma (2 papers, 2018 to 2024). A benign or malignant brain and spinal cord tumor that arises from glial cells (astrocytes, oligodendrocytes, ependymal cells). "We acknowledge that PSTPIP1's role warrants further investigation, and future studies could explore its potential as a prognostic biomarker or therapeutic target in gliomas." (PMID 39492838, 2024).
lupus (2 papers, 2022 to 2023). "Interestingly, among the 43 PAMI cases reported in this review, one presented with a lupus-like phenotype (patient N° 8), suggesting that including the PSTPIP1 gene in lupus genetic panels might be of interest." (PMID 37628706, 2023).
PAPA syndrome (2 papers, 2021 to 2022). "In particular, PAPA syndrome is caused by dysfunction of the proline-serine-threonine phosphatase-interacting protein 1 (PSTPIP1), which acts as a cytoskeleton-associated adaptor." (PMID 35883675, 2022).
SAPHO syndrome (2 papers, 2021 to 2022). SAPHO syndrome (acronym for Synovitis, Acne, Pustulosis, Hyperostosis and Osteitis) is an auto-inflammatory disease, mainly characterized by the association of neutrophilic cutaneous involvement and chronic osteomyelitis. "Two mutations encoding PSTPIP1 gene (A230T and E250Q) were found in PAPA patients, and the absence of PSTPIP2 triggers SAPHO syndromes." (PMID 34262554, 2021).
autoimmune disease (1 paper, 2015). A disorder resulting from loss of function or tissue destruction of an organ or multiple organs, arising from humoral or cellular immune responses of the individual to their own tissue constituents. "Overlapping of some gene locations of different autoimmune diseases has been known and supports common pathogenic gene variants (PTPN 22, Csk, PAG, PSTPIP1, PDCD1, SLC9A3R1, CARD15, and SUMO4) transcript within these diseases." (PMID 26339139, 2015).
bladder cancer (1 paper, 2016). "Finally, some of the dysregulated proteins found in this study have not been reported previously in bladder cancer, including NEP, Factor XIIIB, PSTPIP1, TFIIHp89 and CX3CR1." (PMID 27626805, 2016).
common variable immunodeficiency (1 paper, 2022). "Moreover, the collection of diseases associated with PSTPIP1 mutations has expanded to include common variable immunodeficiency (CVID)." (PMID 35152348, 2022).
COVID-19 (1 paper, 2021). A disease caused by infection with severe acute respiratory syndrome coronavirus 2.
Crohn disease (1 paper, 2010). A gastrointestinal disorder characterized by chronic inflammation involving all layers of the intestinal wall, noncaseating granulomas affecting the intestinal wall and regional lymph nodes, and transmural fibrosis. "However, recently a CCTG repeat in the PSTPIP1 promoter of patients with Crohn’s disease or aseptic abscesses syndrome was identified that may play a pathogenic role in these diseases." (PMID 21532836, 2010).
hereditary periodic fever syndrome (1 paper, 2008). An instance of periodic fever syndrome that is caused by an inherited modification of the individual's genome. "NLRP3, NOD2, MEFV, and PSTPIP1 are the genes responsible for 4 of the syndromes collectively termed hereditary periodic fever syndromes (HPFS)." (PMID 18576390, 2008).
insulin dependent diabetes mellitus (1 paper, 2010). "Specifically, Pstpip1, Il18r1, Sult2a1 overlapped the QTLs of “Non-insulin dependent diabetes mellitus (Niddm)”." (PMID 21124896, 2010).
lung adenocarcinoma (1 paper, 2025). A carcinoma that arises from the lung and is characterized by the presence of malignant glandular epithelial cells. "SPI1 and PSTPIP1 were discovered as novel early prognostic biomarkers relevant to innate immune response in lung adenocarcinoma." (PMID 41144480, 2025).
Pancytopenia (1 paper, 2020). An abnormal reduction in numbers of all blood cell types (red blood cells, white blood cells, and platelets). "Recently, severer cases showing growth failure, pancytopenia, hepatosplenomegaly with hyperzincemia and hypercalprotectinemia have been identified to be associated with particular PSTPIP1 mutations and designated as PSTPIP1-associated myeloid-related proteinemia inflammatory (PAMI) syndrome." (PMID 32256502, 2020).
renal fibrosis (1 paper, 2016). A final common manifestation of a wide variety of chronic kidney diseases characterized by glomerulosclerosis and tubulointerstitial fibrosis. "The list of genes includes Fblim1, Epha2, Wisp1, Parvg, Madcam1, Mybpc2, Cdh3, Gpr56, Troap, Pstpip1, Pcdh8, Nlgn2 and Mfap4, genes that based on Pubmed and Kidney and Urinary Pathway Knowledge Base12 searches have not been previously associated with renal fibrosis." (PMID 27189340, 2016).
rheumatoid arthritis (1 paper, 2019). A chronic, systemic autoimmune disorder characterized by inflammation in the synovial membranes and articular surfaces. "In another example, for rheumatoid arthritis, PSTPIP1 emerged as the only causal gene at its locus: its low expression is significantly associated with the risk of rheumatoid arthritis in the general population (PTWMR = 1.24 × 10−7)." (PMID 31341166, 2019).
cancer (2 papers, 2020 to 2022). A tumor composed of atypical neoplastic, often pleomorphic cells that invade other tissues. "It was found that eight proteins (ADD2, DEF6, DOK3, ENO2, FMNL1, MICALL2, PARVG, and PSTPIP1) in KIRC cancer were more highly expressed in tumor tissues (100%), compared with normal tissues." (PMID 36428765, 2022). "F-BAR proteins such as PSTPIP1 dysfunction underpins a range of diseases such as neurodegenerative disorders, cancer, autoimmune and auto-inflammatory disorders." (PMID 32164332, 2020). "Such parallel studies are important given that actin-associated proteins are implicated in a diverse range of diseases, for example ranging from autoinflammatory disease (e.g., PSTPIP1) to cancer (e.g., BIN1)." (PMID 32164332, 2020).
infection (2 papers, 2020 to 2023). The state of being infected such as from the introduction of a foreign agent such as serum, vaccine, antigenic substance or organism. "It was shown that after infection with ZY05719 and △MetQ respectively, abundances of Pstpip1 and Hmox1 increased, while Src abundance was reduced in the △MetQ treated group, which was in agreement with the LC–MS results." (PMID 33125582, 2020).
tumor (2 papers, 2022). "However, the significantly increased expression of the PSTPIP1 homologous gene was confirmed in tumor tissues from the SKCM mice that responded to the anti–PD-L1 treatment." (PMID 35571056, 2022). "Given that LUAD differentiation can influence the expression of PD-L1, we further explored the correlation between PSTPIP1/PILRA and tumor differentiation." (PMID 35571056, 2022). "Further study is needed to verify the clinical value of PSTPIP1 and PILRA in the additional samples and to explore their molecular functions in tumor immune regulation." (PMID 35571056, 2022). "Compared to PD-L1–negative LUAD tissues, the protein levels of PSTPIP1 and PILRA were relatively increased in the PD-L1–positive tissues, and the expression of PSTPIP1 and PILRA positively correlated with the tumor-infiltrating lymphocytes." (PMID 35571056, 2022). "Except for PSTPIP1 and PILRA, the other genes with high scores have been identified to have functionally relevant roles in the immune checkpoint, tumoral immune cells, and immune infiltration, while few studies have reported the role of PSTPIP1 and PILRA in tumor immunity." (PMID 35571056, 2022). "Therefore, to some extent, we can exclude the possibility that PSTPIP1 and PILRA levels are correlated with tumor differentiation rather than immune biomarkers." (PMID 35571056, 2022).
autosomal dominant disease (1 paper, 2021). Autosomal dominant form of disease. "It is an autosomal dominant disease caused by a mutation in the proline serine threonine phosphatase-interacting protein 1 (PSTPIP1) gene, leading to overproduction of the pro-inflammatory cytokine IL-1." (PMID 34202154, 2021).
PSTPIP1 also shares sentences with these, for which no sentence is quoted: Arthritis (4 papers); osteomyelitis (3); Blau syndrome (2); hidradenitis suppurativa (2); Majeed syndrome (2); PASH syndrome (2); ulcerative colitis (2); AIDS (1); bacterial infections (1); breast carcinoma (1); cryopyrin-associated periodic syndrome (1); Dent Disease 2 (1); Dowling-Degos disease (1); gastric cancer (1); inflammation (1); inflammatory bowel disease (1); juvenile idiopathic arthritis (1); Keratitis-Ichthyosis-Deafness syndrome (1); macrophage activation syndrome (1); multiple myeloma (1); pachyonychia congenita (1); proctitis (1); pustular psoriasis (1); skin ulceration (1).